IL1B (interleukin 1 beta)
Diseases named in the same sentence as IL1B in open-access papers (continued):
Sharing a sentence is not in itself a finding about the gene and the disease.
COVID-19 (continued). "We speculate that administration of intravenous activated autologous platelet-rich plasma (aaPRP), which contains interleukin-1 receptor antagonist (IL-1RA), would lower IL-1β levels and benefit the severe and critical COVID-19 patients." (PMID 34306796, 2021). "Considering the pathological role of IL-1β signaling in CS, several drugs targeting IL-1β signaling, including IL-1β antagonist canakinumab and IL-1 receptor antagonist anakinra, may offer clinical benefits in the treatment of COVID-19, particularly in CS." (PMID 34234112, 2021). "Additionally, mTOR-I when given at the early onset of the cytokine storm phase can hinder the IL-6 pathway and NLRP3 inflammasome-dependent release of IL-1β, thus preventing the progression to severe forms of COVID-19." (PMID 34497515, 2021). "Of note, the levels of IL-1β in COVID-19 patients were comparable to those seen in monogenic autoinflammatory disorders of IL-1β excess, whereas the levels of IL-18 were lower in COVID-19 patients relative to the levels observed in autoinflammatory IL-18opathies that predispose to MAS." (PMID 33232303, 2021). "Novel anti-inflammatory approaches, such as the antagonists for IL-6 or IL-1β signaling, in addition to antithrombotic treatments, might have a greater effect in preventing thrombosis and death in COVID-19 than either therapy alone." (PMID 34768445, 2021). "The expression of these submodules in the blood transcriptome of this small number of COVID-19 patients revealed variation in IL-1β and IL-6 bioactivity over the period of hospitalization, with higher expression seen earlier during hospital admission and a reduction as patients recovered." (PMID 33319166, 2021). "In our cohort, levels of IL-1β and IL-18 were higher in patients with COVID-19 compared with HVs." (PMID 33232303, 2021). "In this study, microscopic analysis in combination with luminescent assays show the formation of NLRP3 and ASC puncta, caspase-1 activation, and IL-1β secretion in PBMCs (Peripheral blood mononuclear cells) of COVID-19 patients during the disease and in postmortem lung tissues." (PMID 33467177, 2021). "Some patients with COVID-19 develop a cytokine storm syndrome, characterized by overproduction of early response pro-inflammatory cytokines such as tumor necrosis factor, interleukin [IL]-6, and IL-1β." (PMID 35071250, 2021). "Among the cytokines, interleukin-1β (IL-1β) is one of the most overexpressed in COVID-19." (PMID 34306796, 2021). "Moreover, a much larger proportion of these neutrophils was in a hyperactivated state in COVID-19 patients, marked by upregulated IL1B, CXCL8 and S100A12 expression." (PMID 34226537, 2021). "Other cytokines like IL-1β and IL-6, which have been linked to COVID-19 severity and the ensuing cytokine storm, did not exhibit comparable increases in pulmonary neutrophils and did not elicit IL-8 release from blood neutrophils in vitro." (PMID 34403366, 2021). "Thus, WS can be considered for the investigation to mitigate cytokine storm in patients with COVID-19, with special reference to IL-1β and IL-6." (PMID 34012390, 2021). "Therefore, potential targeting of IL6 induced by IL1B is an exciting therapeutic approach in COVID-19." (PMID 33757410, 2021). "As clinical deterioration in COVID-19 occurs after peak viral replication in the airways has subsided, we tested the hypothesis that IL-1β and IL-6 activity was also related to disease severity." (PMID 33319166, 2021). "Experiments performed with ex vivo freshly isolated monocytes showed that unstimulated monocytes from patients with COVID-19 were able to spontaneously secrete high levels of IL-6, IL-8 and IL-1β which persisted, even though at lower levels, in recovered individuals for several weeks after recovery." (PMID 33060840, 2021). "In addition, IL-1β and its receptor are therapeutic targets in MI and HF; additionally, IL-1β inhibitors improve hyperinflammation and the clinical outcomes of patients with COVID-19." (PMID 33404925, 2021).
COVID-19 (continued). "Certainly, it is undoubtful that IL-1β plays a key role in the pathological process of COVID-19." (PMID 34725309, 2021). "Depression and COVID-19 demonstrate shared patterns of immunological function, especially around a pro-inflammatory state characterized by elevation in cytokines including IL-6, TNFα, and IL-1β." (PMID 33967944, 2021). "Higher IL-1β levels are observed in the plasma of severely ill patients with COVID-19." (PMID 34360684, 2021). "Variants in cytokine genes such as IL1B, IL1R1, IL1RN, IL6, IL17A, FCGR2A, and TNF could be related to disease susceptibility and cytokine storm, and/or COVID-19 complications (e.g., venous thrombosis)." (PMID 33868239, 2021). "Severely ill patients hospitalised with COVID-19 exhibit increased levels of many cytokines, including Interleukin (IL)-1β, IL-2, IL-6, IL-7, IL-8, IL-10, IL-17, granulocyte colony stimulating factor (G-CSF), monocyte chemoattractant protein 1 (MCP-1) and tumor necrosis factor (TNF)." (PMID 34205262, 2021). "In severe cases of COVID-19 patients, increased IL-1α and IL-1β have been detected." (PMID 34054828, 2021). "Blockage of IL-1β for COVID-19 is studied in numerous studies." (PMID 34306796, 2021). "Moreover, clinical trials are underway to investigate effects of IL6 receptor and IL1B signaling blockade on COVID-19 treatment." (PMID 34975885, 2021). "Likewise, serum IL-1β, IL-6, and IL-8 levels were positively correlated with critical COVID-19 in-hospital death (r = 0.4929; r = 0.4539; r = 0.6002, respectively)." (PMID 34276659, 2021). "As is the case with COVID-19, there is an increase in IL-1β, IL-6, and C-reactive protein (CRP)." (PMID 34367545, 2021). "Additionally, active intracellular caspase-1 was detected in PBMCs obtained from COVID-19 patients, and the maintenance of these cells in culture resulted in increased active caspase-1 and IL-1β in the supernatant." (PMID 34977191, 2021). "COVID-19 patients who succumb to pneumonia and hypoxia had one hallmark feature of the profound inflammatory state that marked elevation of serum inflammatory cytokines (IL-6, IFN-γ, IL-1β, TNF-α and TGF-β) and chemokines (CCL2, CCL5, CXCL8 and CXCL10)." (PMID 34313585, 2021). "In parallel, a critical reduction of IL-1β, IL-1RA, IL-6, and TNF-α concentration was evident 2 days after MSC infusion, mimicking the effectiveness of other immunomodulatory agents, such as baricitinib, in dampening COVID-19-associated inflammation." (PMID 34078447, 2021). "The response to viral infection results in the release of several proinflammatory molecules, including histamine, tryptase, IL-1β, CCL2, IL-6, GM-CSF, and TNF-α, which are implicated in COVID-19 and appear to have relationship with pulmonary damage and fibrosis." (PMID 33808490, 2021). "For example, the proinflammatory cytokine IL-1β is increased in people with COVID-19." (PMID 33677470, 2021). "Finally, C5a, C3a, factor P, and serum IL-1β, IL-6, and IL-8 levels positively correlated with critical COVID-19 in-hospital deaths." (PMID 34276659, 2021). "Immune effector cells can release large amounts of pro-inflammatory cytokines (TNF-α and TGF-β, IFN-α, IFN-γ, IL-1β, IL-6, IL-12, IL-18 or IL-33) and chemokines (CCL2, CCL3, CCL5, CXCL8, CXCL9 or CXCL10) in response to SARS-CoV-2 infection." (PMID 34360616, 2021). "Most COVID-19 patients exhibit increased circulating levels of IL-6, IL-1b, and TNF, as well as IL-2, IL-8, reflecting the disease severity, which results in massive systemic immunosuppression and in lymphopenia and neutrophilia, two key hematological features of COVID-19." (PMID 33815868, 2021). "One downstream indicator of pyroptosis is IL-1β; the evidence of high serum IL-1β may be one indicative of pyroptosis in COVID-19-related lung inflammation." (PMID 32834892, 2020).
COVID-19 (continued). "Future investigations will be essential to clarify whether IL-6, IL-1β, and other pro-inflammatory cytokines produced during COVID-19 may affect tumor cells and the TME, possibly supporting the use of anti-cytokine therapies in cancer patients with COVID-19." (PMID 33194755, 2020). "Similarly, a greater proportion of CD14++ CD16− IL1β+ monocytes were detected in COVID-19 patients by RNA sequencing, which found expression in CD14++ monocytes of pro and anti-inflammatory genes were up and down-regulated, respectively when compared to HCs." (PMID 33123152, 2020). "In viral infections, including COVID-19, elevated levels of the pro-inflammatory cytokine IL-18, that derives from the inflammasome as IL-1β, are found along with high levels of ferritin, thus replicating the events commonly observed in the macrophage activation syndrome." (PMID 32719685, 2020). "A diet rich in such compounds may help patients with COVID-19 to reduce their inflammation due to the hyper-activation of cytokines such as TNFα, IL-1β, IL-6, and IL-8." (PMID 33322757, 2020). "The remainder of fecal cytokines analyzed (IL-1β, IL-1ra, IL-6, IL-8, IL-17, TNFα) were not significantly different in COVID-19 patients compared to controls nor associated with severity of disease." (PMID 32909002, 2020). "Interestingly, TNF and IL1B, major genes in the inflammatory response, were identified as COVID-19-specific and commonly up-regulated genes, respectively." (PMID 32651212, 2020). "In this regards, bioactive phytochemicals, such as polyphenols may become promising tools for the treatment of COVID-19 in reducing the hyperactivation of cytokines such as TNFα, IL-1β, IL-6, and IL-8." (PMID 33322757, 2020). "Another inhibitory cytokine that may help in patients with COVID-19 is the newest cytokine of the IL-1 family, IL-38, which is produced by some immune cells including macrophages and B cells, IL-38 inhibits IL-1β and other pro-inflammatory cytokines." (PMID 32752010, 2020). "COVID-19 induces a pro-inflammatory generation and secretion of cytokines including IL-1b and IL-6 via the toll like receptors (TLR) that causes the production of active mature IL-1b which is a mediator of lung inflammation, fever and fibrosis." (PMID 32256705, 2020). "Besides IL-6, also IL-1β has been reported to be elevated in COVID-19 patients as compared to controls." (PMID 33194755, 2020). "In this context, IL-1β release has been proposed as one of the key inflammatory mediators in COVID-19 and could potentially exacerbate bradykinin-induced vascular permeability in these patients." (PMID 33327440, 2020). "Moreover, there are different clinical trials registered to study the efficacy and safety of Canakinumab (anti-IL-1β monoclonal antibody) in COVID-19-induce pneumonia (NCT04362813, NCT04348448) and COVID-19 cardiac injury (NCT04365153)." (PMID 33193349, 2020). "Multiple anti-inflammatory agents are thus currently undergoing clinical evaluation for COVID-19, including not only corticosteroids but also biologicals that target inflammatory cytokines, such as anti-IL-6 or anti-IL-1β agents, and other immune-modulatory agents." (PMID 33194755, 2020). "Indeed, SAgs induce an inflammatory cytokine signature similar to that which predicts severity and death in COVID-19, including IL-6, TNFα, IL-8, and IL-1β." (PMID 32989130, 2020). "Moreover IL-1β, IL-2, IL-5, IL-18, TNFα, and GM-CSF became detectable in all the samples following co-culture between resting PBMCs from COVID-19 patients and DPSCs." (PMID 33634100, 2020). "However, CoVs, such as COVID-19, also present as a hyperactivation of the inflammatory response that results in increased production of inflammatory cytokines such as interleukin (IL)-1β and its downstream molecule IL-6." (PMID 33149733, 2020).
COVID-19 (continued). "Patients with COVID-19 had high amounts of IL-1β, IFN-γ, IP-10, and MCP-1, indicating an activated Th1 response; besides, SARS-CoV-2 could also initiate increased secretion of Th2 cytokines, especially IL-10, which is different from SARS-CoV infection." (PMID 32426374, 2020). "Decreased expression and secretion of IL-1β and IL-6 was observed in the COVID-19 patients." (PMID 33708109, 2020). "COVID-19 early recovery stage was characterized by CD14 ++ monocytes with high inflammatory gene expression as well as by the abundance of CD14 ++IL1β + cells, while T cells decreased remarkably, compared with both late recovery stage and healthy control subjects." (PMID 33129318, 2020). "Although mechanistic insight into the host inflammatory response to COVID-19 is still limited, it is likely that both IL-1α and IL-1β play a central role in the development of the exuberant, maladaptive inflammatory response leading to life-threatening states in some patients." (PMID 33442386, 2020). "Indeed, in COVID-19, very critical patients display a cytokine storm syndrome with an increased secretion of interleukin (IL)-6, IL-1β, IL-17, IL-8, tumor necrosis factor (TNF)-α, interferon (IFN)-γ and other pro-inflammatory mediators." (PMID 32708322, 2020). "Interestingly, ACE2 shedding is enhanced not only by binding with spike protein, but also by IL-1β and TNFα inflammatory cytokines, cytokines that are secreted at relatively high concentration in COVID-19 patients." (PMID 32708755, 2020). "Besides anakinra, another IL-1 antagonist was evaluated in COVID-19, that is, the anti-IL-1β monoclonal antibody canakinumab." (PMID 33442386, 2020). "The massive release of TNF-α, IFN-γ, IL-1β, IL-8, MCP-1, and IP-10 seen in acute phase of COVID-19 patients may probably be linked to pyroptosis, especially in lymphocytes through the NLRP3 inflammasome activation." (PMID 33193349, 2020). "Considering its close relation to ARDS, and also that neutrophilia, high levels of IL-1β, IL-6, and D-dimer are poor outcome predictors in COVID-19, some authors suggest that NET may play a major role in its pathogenesis." (PMID 32962761, 2020). "However, we also found that severe COVID-19 is accompanied by the IFN-I response in addition to the TNF/IL-1β response." (PMID 32651212, 2020). "The binding of COVID-19 to TLRs activates the formation of active IL-1β and IL-6." (PMID 32695683, 2020). "Furthermore, Colchicine has been successfully tested as inhibitor of NLRP3 inflammasome, improving survival outcomes in COVID-19 patients since it suppresses caspase-1 activation and subsequent IL-1β and IL-18 processing." (PMID 33193349, 2020). "Other inflammatory cytokines such as IL-1β, IL-4, IL-2, IL-10, and TNFα have also been found to increase, with IL-6 and TNFα still increased in patients with a neurological symptom profile, and IL-1β was upregulated in patients with persistent COVID-19 symptoms." (PMID 41516418, 2026). "Thus, evaluating the tissue expression of IL-6, IL-1β, and IL-18 in a sensory nerve could provide information about neuroinflammation related to neuropathic pain in post-COVID-19 conditions." (PMID 41516235, 2025). "This leads to the upregulation of pro-inflammatory cytokines such as Interleukin-6 (IL-6), TNF-α, and IL-1β and contributing to the cytokine storm, a hyperinflammatory state characterized by the uncontrolled systemic release of cytokines and pulmonary pathology seen in critical COVID-19 patients." (PMID 41176818, 2025). "The results showed that COVID-19 patients had significantly higher levels of all three cytokines compared to the control group: IL-6 at 165.85 ng/mL (±20.13) vs. 86.68 ng/mL (±17.30); IL-1β at 52.30 ng/mL (±11.71) vs. 6.30 ng/mL (±6.61); and TNF-α at 179.54 ng/mL (±28.92) vs. 18.50 ng/mL (±4.25)." (PMID 39201618, 2024).
COVID-19 (continued). "Additionally, the activation of TLRs post-COVID-19 could induce the release of the proinflammatory cytokine IL-1β, suggesting a crucial role for TLR4 in mediating the severity of COVID-19." (PMID 38287815, 2024). "However, we observed a substantial increase in IL-6 and CRP levels associated with the severity of COVID-19, while no such trend was observed for IL-1β and TNF-α." (PMID 39188881, 2024). "etc.)and genes (CD1C, IL1B) that may play important roles in COVID-19." (PMID 39622956, 2024). "Additionally, using a cohort of COVD-19 patients with different disease severity status, the main inflammatory cytokine of the NLRP3 inflammasome pathway, IL-1β, was shown to be significantly upregulated in severe COVID-19 patients when compared to asymptomatic patients." (PMID 38748756, 2024). "Thus, urinary proinflammatory cytokines such as TNFα, IL-1α, IL-1β, IL-16, and IL-17A and total uEVs in COVID-19 patients may identify patients that are prone to renal dysfunction." (PMID 38398672, 2024). "Secondly, the systemic inflammatory response syndrome (SIRS) induced by COVID-19 can lead to a cytokine storm, characterized by the release of large quantities of pro-inflammatory cytokines such as interleukin-6 (IL-6), interleukin-1β (IL-1β), and tumor necrosis factor-alpha (TNF-α)." (PMID 38999316, 2024). "Interestingly, IL1-B and TNF-a blood levels were associated with post-COVID-19 illness and the use of flavonoid-derived compounds could mitigate post-COVID-19 symptoms." (PMID 36838279, 2023). "Furthermore, the Th17 response in COVID-19 patients instigates pro-inflammatory cytokine IL-17, which employs monocytes and neutrophils to pulmonary circulation and initiates a surge of surplus cytokines such as IL-1β and IL-6." (PMID 37051070, 2023). "Both COVID-19 and RA exhibit an excessive immune response and cytokine imbalance, which are caused by the overactivation of T cells (especially Th1 and Th17 cells) that secrete a large number of cytokines, including TNF-α, IL-1β, IL-6, IL-8, IL-17, and GM-CSF, leading to tissue damage." (PMID 37163438, 2023). "Therefore, IL-1β should be considered a critical immune mediator in the pathogenesis of COVID-19." (PMID 37654571, 2023). "Particularly, an increased susceptibility for Candida infections in critically ill COVID-19 patients was suggested by the observation of impaired immune response to those pathogens characterized by the abrogated release of IL-6, TNF, IL-1α, and IL-1β toward Candida albicans." (PMID 36675940, 2023). "First, we studied the profile of different soluble pro-inflammatory cytokines (GM-CSF, TNF-α, IFN-γ, IL-1β, IL-2, IL-6, IL-7, IL-10, IL-17A, IL-21) and chemokines mediating monocyte and neutrophil recruitment (IL8, CCL3), whose exacerbated production is associated with severe COVID-19." (PMID 36675231, 2023). "Inflammatory markers and pro-inflammatory cytokines, such as CRP, ferritin, IL-1β, IL-8, TNF-α, and MCP1, show a significant increase in their serum concentrations, and the elevated neutrophil-to-lymphocyte ratio is associated with more severe cases of COVID-19 that can lead to death more easily." (PMID 37408184, 2023). "Based on the results of the in vivo COVID-19 cytokine storm study, we focused on the IL-1β, IL-2, IL-6, TNFα, IL-4, and IL-10 molecular pathways as the key elements of the inflammatory response in order to identify the molecular mechanisms of peptidergic regulation of the cytokine storm in COVID-19." (PMID 37686182, 2023). "To determine the biomarker reliability of the inflammasome signaling proteins caspase-1, ASC, IL-1β and IL-18, we plotted ROC curves for each protein using data from healthy subjects and from patients that tested positive for COVID-19 and presented an active infection." (PMID 37168848, 2023). "GCF IL-1β might be a potential biomarker for predicting COVID-19 occurrence." (PMID 36718446, 2023). "Additionally, IL-1β, along with IL-6 and TNF, has been associated with post-COVID-19 sequelae." (PMID 38090572, 2023).